VSIG2 (V-set and immunoglobulin domain containing 2)
Synonyms: CTH; CTXL; 2210413P10Rik
Tractability: Antibody: its Gene Ontology location is reachable by antibodies, with high confidence; UniProt predicts a signal peptide or a membrane-spanning region.
Gene: Protein-coding gene on chromosome 11 (124,747,472 to 124,752,255, reverse strand). Ensembl gene ENSG00000019102.
Subcellular location: Membrane
Subcellular location (Human Protein Atlas): Nucleoplasm
Gene Ontology:
Cellular component: membrane; plasma membrane
Genetic constraint (gnomAD): Loss-of-function variants: 28 observed, 30.03 expected, observed/expected ratio (o/e) 0.93, 90% interval 0.69 to 1.28. The upper end of that interval is the gene's LOEUF score, 1.28, which puts it in group 5 of 6, group 1 being the genes least tolerant of losing a copy. Missense variants: 416 observed, 404.2 expected, observed/expected ratio (o/e) 1.03, 90% interval 0.95 to 1.12. Synonymous variants: 177 observed, 176.56 expected, observed/expected ratio (o/e) 1, 90% interval 0.89 to 1.14.
Homologues: Orthologues: chimpanzee VSIG2 (99% identical), macaque VSIG2 (97% identical), dog VSIG2 (86% identical), pig VSIG2 (85% identical), rat Vsig2 (84% identical), guinea pig VSIG2 (82% identical), mouse Vsig2 (82% identical), tropical clawed frog vsig2 (38% identical). Paralogues in human: ESAM (31% identical), VSIG1 (28% identical), IGSF11 (28% identical), CXADR (25% identical), CLMP (23% identical), JAM3 (20% identical), GPA33 (20% identical), VSIG8 (20% identical), MXRA8 (19% identical), F11R (18% identical), JAM2 (18% identical), MUC15 (14% identical), and 2 more.
Diseases named in the same sentence as VSIG2 in open-access papers:
VSIG2 is named in the same sentence as 23 diseases in open-access papers, as found by Europe PMC text mining. Sharing a sentence is not in itself a finding about the gene and the disease. The quoted sentences say what the papers report.
colorectal cancer (2 papers, 2023 to 2025). A primary or metastatic malignant neoplasm that affects the colon or rectum. "Further, VSIG2 was identified as a significantly dysregulated differential protein in colorectal cancer (CRC) through iTRAQ labeling proteomics and TMT labeling phospho-proteomics analysis of CRC tissues and adjacent normal tissues." (PMID 37626304, 2023).
bladder cancer (1 paper, 2021). "VSIG2 has been found to be differentially expressed in endometrial cancer, and to be significantly associated with bladder cancer risk." (PMID 34787244, 2021).
gastric cancer (1 paper, 2025). A primary or metastatic malignant neoplasm involving the stomach. "Restoring VSIG2 expression or pharmacologically disrupting the ANXA2–FBXW10 axis might represent a promising therapeutic avenue for high-risk gastric cancer patients." (PMID 41185558, 2025). "The results revealed that the level of VSIG2 in gastric cancer cell lines was significantly lower than that in normal gastric epithelial cells." (PMID 41185558, 2025).
gastritis (1 paper, 2025). Inflammation of the stomach. "Collectively, these findings suggest that the four biomarkers, namely, CHI3L1, FCGBP, VSIG2, and TFF2, hold the potential for diagnosing GC, particularly in cases of gastritis and early‐stage GC." (PMID 40084401, 2025).
glucose metabolism disorders (1 paper, 2025). "A clinical study revealed that the plasma levels of V-set and immunoglobulin domain-containing 2 (VSIG2) are related to glucose metabolism disorders and the occurrence of T2DM." (PMID 41550874, 2025).
Insulin resistance (1 paper, 2019). Increased resistance towards insulin, that is, diminished effectiveness of insulin in reducing blood glucose levels. "SGPP2, IGSF3, and VSIG2 are novel biomarkers for the development of insulin resistance." (PMID 30678306, 2019).
ischemia (1 paper, 2022). A hypoperfusion of the BLOOD through an organ or tissue caused by a PATHOLOGIC CONSTRICTION or obstruction of its BLOOD VESSELS, or an absence of BLOOD CIRCULATION. "Among subjects with CAD, two proteins were significantly increased in subjects with ischemia on MPI compared to those without ischemia on MPI: VSIG2 and GIF." (PMID 35263363, 2022).
lung adenocarcinoma (1 paper, 2023). A carcinoma that arises from the lung and is characterized by the presence of malignant glandular epithelial cells. "It is worth noting that VSIG2 expression is positively associated with the development and poor prognosis of AML, primary lung adenocarcinoma, and PDAC, while VSIG2 suppresses muscle invasive bladder cancer as well as COAD." (PMID 37626304, 2023).
lymph node metastasis (1 paper, 2025). "We found that patients with low VSIG2 levels were more likely to have lymph node metastasis, vascular invasion, high TNM stage and larger tumors." (PMID 41185558, 2025).
lymphoid tumors (1 paper, 2014). "We have previously reported on the activation of neuronal neurogranin (Nrgn) in T-cell lymphomas induced by SL3-3 integration in the Esam/Vsig2/Nrgn/Siae/Spa17 locus where the Nrgn expression level in lymphoid tumors corresponded to brain levels." (PMID 24886479, 2014).
pancreatic cancer (1 paper, 2023). "Specifically, Cancer cell 1 expressed Gcnt3, Mmp7, and Vsig2, which are associated with the epithelial/classical subtype of pancreatic cancer cells." (PMID 37998349, 2023).
prostate carcinoma (1 paper, 2023). A carcinoma that arises from epithelial cells of the prostate gland. "After constructing the prognostic prediction model, SLPI, VSIG2, CENPF, SLC7A1, SMC4, and ITPR2 were finally regarded as the key genes in the prognosis of patients with prostate cancer." (PMID 36937411, 2023).
systemic lupus erythematosus (1 paper, 2022). An autoimmune multi-organ disease typically associated with vasculopathy and autoantibody production. "Moreover, the single nucleotide polymorphisms (SNPs) of VSIG2 are strongly associated with serologic profile and cytokine phenotype in systemic lupus erythematosus (SLE)." (PMID 36189222, 2022).
cancer (9 papers, 2016 to 2025). A tumor composed of atypical neoplastic, often pleomorphic cells that invade other tissues. "Consistent with previous data, the expression level of VSIG2 in cancer tissues was significantly lower than that in adjacent tissues." (PMID 41185558, 2025). "The results revealed that the expression of VSIG2 in cancer tissues was significantly lower than that in adjacent tissues." (PMID 41185558, 2025). "Our results reveal that low VSIG2 levels in GC drive the proliferation and migration of cancer cells." (PMID 41185558, 2025). "An abolishment of the immune responses against cancer cells was also sustained by results on VSIG2, a transmembrane protein that ensures tumor immune surveillance and was found to be down-regulated in CRC." (PMID 39195201, 2024). "Subsequently, IHC was performed to further clarify VSIG2 expression in cancer and para-cancer tissues." (PMID 37626304, 2023). "However, it appears that VSIG2 functions as a tumor suppressor gene to ensure tumor immune surveillance rather than an immune checkpoint molecule in this particular cancer type." (PMID 36189222, 2022). "High expression and methylation of VSIG2 correlated with poor survival in these cancer patients." (PMID 36189222, 2022). "In Elyada’s scRNA-seq analysis, ductal cancer cells in human PDAC were clustered in two major subtypes: the classic (by TFF1, TFF2, LYZ, VSIG2, and CEACAM6 marker genes) and secretory (by SPP1, CLU, CTGF, and COL18A1 marker genes) subtypes." (PMID 34035226, 2021). "Twelve pairs of cancer and adjacent normal tissues were randomly selected from the samples of PDAC patients for Western blotting analysis, which showed that VSIG2 was overexpressed in tumor tissues, while the protein expression in adjacent tissues was extremely low." (PMID 37626304, 2023). "The function of VSIG2 in cancer has not been described previously, although this gene may serve as a potential biomarker for BCLA." (PMID 34589112, 2021).
tumor (6 papers, 2021 to 2026). "In conclusion, VSIG2, as a tumor-associated antigen, is expected to become a novel neoplasm marker in the immunological examination of PDAC, thereby improving the early screening rate and diagnosis rate of PDAC." (PMID 37626304, 2023). "Clinicopathological analysis according to the information of 62 patients with PDAC unfolded that VSIG2 overexpression was related to vascular invasion (P=0.024), and the expression level of VSIG2 was positively associated with tumor size (P<0.01)." (PMID 37626304, 2023). "In this model, low expression of FCGBP (IgGFc‐binding protein) and VSIG2 (V‐set and Ig domain‐containing protein 2) was associated with tumor progression, but their roles and mechanisms in GC remain unclear." (PMID 40084401, 2025). "Cell growth was accelerated after silencing VSIG2, suggesting a tumor suppressor role of VSIG2 in GC." (PMID 40084401, 2025). "Taken together, these experimental results indicate that VSIG2 can weaken the proliferative ability of tumor cells in GC." (PMID 41185558, 2025). "By integrating functional tumor assays and mechanistic analysis, our study is the first to report that VSIG2 acts as a membrane-anchored negative regulator of ANXA2 trafficking rather than a classical immune checkpoint." (PMID 41185558, 2025). "Low VSIG2 expression is closely related to tumor size, lymph node metastasis, TNM stage and vascular invasion in GC patients." (PMID 41185558, 2025). "Compared with that of the control group, the tumor volume of HGC27 cells overexpressing VSIG2 in nude mice was significantly reduced." (PMID 41185558, 2025). "V-set and immunoglobulin domain-containing 2 (VSIG2) is an emerging B7-like immune checkpoint whose expression topography has quietly shifted from a “thymocyte relic” to a decisive regulator of tumor–immune crosstalk." (PMID 41185558, 2025). "To further study the effect of VSIG2 on the progression of GC, we designed a tumor formation experiment in nude mice." (PMID 41185558, 2025). "The experimental conclusion about LAMTOR2-mediated VSIG2 oncogenic effect on PDAC was ulteriorly elucidated using subcutaneous xenograft tumor model." (PMID 37626304, 2023). "Our study elucidated another mechanism of VSIG2 in promoting the malignant progression of PDAC besides mediating the tumor immune response, and provided an experimental basis for further evaluation of its value as a molecular marker and therapeutic target." (PMID 37626304, 2023). "The latest findings suggested that VSIG2 functioned as a key molecule in tumor and immune cells." (PMID 40084401, 2025). "Transcriptomic atlases now reveal that VSIG2 is not confined to the thymus but is highly enriched in gastric and colonic epithelia, renal tubules, and critically tumour-associated macrophages and B cells." (PMID 41185558, 2025). "Similarly, VSIG2 was significantly overexpressed in tumor compared to para-tumor according to TCGA and GSE22780 dataset." (PMID 37626304, 2023). "Additionally, subcutaneous xenograft tumor model and clinical samples analysis were implemented to further elucidate the oncogenic effect of VSIG2 on PDAC in vivo and clinically." (PMID 37626304, 2023). "Since these cells are normally the most abundant antigen-presenting cells in tumor tissues, dissecting the role of VSIG2 in these cells may have implications for understanding the biology of T-cell activation in the tumor microenvironment." (PMID 36189222, 2022). "Single-cell interrogations further revealed that VSIG2 expression inversely correlates with cytotoxic CD8+ T-cell programs and synergizes with tumour-derived lactate to enforce an immunosuppressive niche." (PMID 41185558, 2025). "The AUC value of the model consisting of the four genes (CHI3L1, FCGBP, VSIG2, and TFF2) outperformed other tumor markers and performed well in predicting the prognosis of GC patients." (PMID 40084401, 2025).
tumor (continued). "The expression level of CCL20, F2, GNPNAT1 and NT5E in the tumor samples was significantly higher than that in normal tissues, while the expression level of B3GALT2, and VSIG2 displayed an opposite expression pattern." (PMID 34787244, 2021). "The effects of VSIG2 on biological effects related to GC progressionin vitro are detected by CCK-8, EdU, Transwell and wound healing assays andin vivo by a nude mouse subcutaneous tumor model and a liver metastasis model." (PMID 41185558, 2025). "Besides, tumor weight was recorded and analyzed after dissection, the role of VSIG2 depletion in tumor weight was impaired after elevation of LAMTOR2 or supplement of mTOR activator, indicating that VSIG2 advanced PDAC progression through LAMTOR2-mediated mTOR activation." (PMID 37626304, 2023). "HGC27 cells with VSIG2 overexpression or not and AGS cells withVSIG2 knockdown or not were injected subcutaneously into nude mice to construct a subcutaneous tumor formation experiment in nude mice." (PMID 41185558, 2025).
VSIG2 also shares sentences with these, for which no sentence is quoted: acute myeloid leukemia (2 papers); pancreatic ductal adenocarcinoma (2); colon adenocarcinoma (1); coronary artery disease (1); endometrial cancer (1); Fuchs endothelial corneal dystrophy (1); Glomerular sclerosis (1); T-cell lymphomas (1).